NFXL1 (nuclear transcription factor, X-box binding like 1)
Synonyms: hOZFP; OZFP; CDZFP; URCC5
Tractability: Antibody: UniProt predicts a signal peptide or a membrane-spanning region. PROTAC: ubiquitination databases record sites on it; its protein half-life has been measured.
Gene: Protein-coding gene on chromosome 4 (47,847,233 to 47,914,667, reverse strand). Ensembl gene ENSG00000170448.
Subcellular location: Membrane
Subcellular location (Human Protein Atlas): Nucleoplasm
Gene Ontology:
Molecular function: DNA-binding transcription factor activity, RNA polymerase II-specific; RNA polymerase II transcription regulatory region sequence-specific DNA binding; DNA-binding transcription factor activity; zinc ion binding
Biological process: regulation of DNA-templated transcription; regulation of transcription by RNA polymerase II
Cellular component: membrane; chromatin; nucleus
Genetic constraint (gnomAD): Loss-of-function variants: 21 observed, 33.23 expected, observed/expected ratio (o/e) 0.63, 90% interval 0.45 to 0.91. The upper end of that interval is the gene's LOEUF score, 0.91, which puts it in group 3 of 6, group 1 being the genes least tolerant of losing a copy. Missense variants: 372 observed, 450.81 expected, observed/expected ratio (o/e) 0.83, 90% interval 0.76 to 0.9. Synonymous variants: 161 observed, 158.7 expected, observed/expected ratio (o/e) 1.01, 90% interval 0.89 to 1.16.
Homologues: Orthologues: chimpanzee NFXL1 (99% identical), macaque NFXL1 (97% identical), rabbit NFXL1 (94% identical), pig NFXL1 (93% identical), dog NFXL1 (92% identical), guinea pig NFXL1 (91% identical), mouse Nfxl1 (90% identical), rat Nfxl1 (88% identical), tropical clawed frog nfxl1 (72% identical), zebrafish nfxl1 (60% identical), Drosophila melanogaster CG15011 (40% identical). Paralogues in human: NFX1 (28% identical).
Diseases named in the same sentence as NFXL1 in open-access papers:
NFXL1 is named in the same sentence as 7 diseases in open-access papers, as found by Europe PMC text mining. Sharing a sentence is not in itself a finding about the gene and the disease. The quoted sentences say what the papers report.
Intellectual disability (1 paper, 2025). "Ten heterozygous NFXL1 missense/nonsense variants have been associated with various neurological disorders which include specific language impairment, speech delay and intellectual disability." (PMID 40430072, 2025).
prostate carcinoma (1 paper, 2024). A carcinoma that arises from epithelial cells of the prostate gland. "Our study found that DNBs and four genes (SCD, NARS2, ALDH1A1, and NFXL1), as relevant factors associated with androgen-related signaling pathways in prostate cancer cells, can be further used as indicators of PCa progression after androgen deprivation therapy." (PMID 39335669, 2024). "In addition, the WGCNA method was used to identify core genes, and when combined with DNBs, four genes including SCD, NARS2, ALDH1A1, and NFXL1 were found to be associated with androgen-related signaling pathways in prostate cancer cells." (PMID 39335669, 2024).
psychosis (1 paper, 2025). "Two homozygous rare deleterious variants in INSR (c.2232-7T>G) and NFXL1 (c.1322G>A; p.Cys441Tyr) were identified, which segregated with severe treatment-resistant psychosis/schizophrenia in two families." (PMID 40430072, 2025). "Our results indicate that INSR and NFXL1 variants may have a role in psychosis that requires to be investigated further." (PMID 40430072, 2025). "Our research indicates a need for further evaluation of INSR, NFXL1 and possibly RYR1 in psychosis in humans." (PMID 40430072, 2025).
schizophrenia (1 paper, 2025). A major psychotic disorder characterized by abnormalities in the perception or expression of reality. "NFXL1 has been reported to play a role in regulating the NFĸB pathway, whose dysregulation is already known to cause neuroinflammation in a subset of schizophrenia patients." (PMID 40430072, 2025).
neurodevelopmental disorder (1 paper, 2015). A behavioral and cognitive disorder with onset during the developmental period that involves impaired or aberrant development of intellectual, motor, or social functions. "Given our consistent findings across cohorts, and in line with the data arising from other neurodevelopmental disorders, we suggest that rare variants in NFXL1 may represent genetic risk factors with incomplete penetrance." (PMID 25781923, 2015).
tumor (1 paper, 2024). "In this study, a novel nomogram was established by integrating the risk score of four genes (SCD, ALDH1A1, NARS2, and NFXL1), age, Gleason score, and tumor stage, each of which was an independent prognostic factor according to the multivariate Cox regression analysis." (PMID 39335669, 2024).
NFXL1 also shares sentences with these, for which no sentence is quoted: neurological disorders (1 paper).